MYC (MYC proto-oncogene, bHLH transcription factor)
Diseases named in the same sentence as MYC in open-access papers (continued):
Sharing a sentence is not in itself a finding about the gene and the disease.
medulloblastoma (continued). "Here, we describe the development and features of a novel orthotopic MYC-driven PDX model of Group 3 medulloblastoma, derived from low-passage tumour spheres of MB-LU-181." (PMID 28417956, 2017). "Highlights of the available literature suggest that targeting Aurora kinase A is an effective way of disrupting MYC stability in c-MYC/MYCN-dependent malignancies including medulloblastoma." (PMID 28333115, 2017). "In the tumour context, MYC and MYCN-driven medulloblastomas exhibit distinct phenotypes due to the preferential ability of MYC to inhibit expression of certain genes via binding to the MIZ-1 transcriptional repressor." (PMID 28398229, 2017). "In MYC-amplified medulloblastoma we also detected a corresponding reduction of AKT and STAT3 phosphorylation and protein levels compared to single drug treatment." (PMID 28159923, 2017). "The Group 3 medulloblastoma mouse models from both these studies demonstrate that the MYC oncogene has to be activated either in stem cells or that the progenitor cell has to be reprogrammed by MYC for transformation to occur." (PMID 28333115, 2017). "In the context of medulloblastoma, work by Ingram and coworkers showed MYC and ABCG2 are highly expressed together at the mRNA and protein levels in 10 Gy radiation-resistant MB cells (DAOY and UW228 parental line)." (PMID 29186899, 2017). "In an orthotopic xenograft modell of MYC-amplified medulloblastoma, Sorafenib and Pazopanib suppressed tumor growth with significantly prolonged survival." (PMID 28159923, 2017). "High expression of OTX2 in medulloblastoma together with c-MYC and MYCN oncogenes, correlates with anaplasticity and unfavorable patient outcome." (PMID 29124525, 2017). "Both primary tumour and xenografts displayed high levels of MYC RNA and MB-LU-181 neurospheres expressed high levels of c-Myc protein compared to DAOY medulloblastoma cells and human dermal fibroblasts cells." (PMID 28417956, 2017). "The MYC genes are often overexpressed or amplified in medulloblastoma, with differential expression of c-MYC and MYCN among the four subgroups." (PMID 28333115, 2017). "In line with the enhanced anti-neoplastic effects of the Vandetanib-GDC-combination our findings demonstrate in MYC-amplified medulloblastoma a further reduction in AKT and STAT3 activity respectively in comparison to single drug application." (PMID 28159923, 2017). "All studies to date, including somatic copy number analysis across 1000 medulloblastoma genomes, identify c-MYC copy number amplifications primarily confined to Group 3 tumors." (PMID 27775567, 2016).
medulloblastoma (continued). "Group 3, especially the MYC+ subgroup differs in its histopathology and gene expression profile from other forms of medulloblastoma, with a high propensity for metastasis portending a poor prognosis." (PMID 27255663, 2016). "Aberration of the MYC oncogene is one of the key molecular pathways in Group 3 medulloblastoma: MYC can induce proliferation as well as apoptosis." (PMID 26883117, 2016). "With regard to medulloblastoma, it is unclear how c-MYC amplification is driving tumor aggressiveness." (PMID 27775567, 2016). "In the only study to our knowledge comparing the two methods, conducted on medulloblastomas for MYC genes including MYC on chromosome 8, FISH would detect less MYC amplified cases than qPCR." (PMID 27184134, 2016). "Cell viability screening of targeted small molecule inhibitors further prioritized IGF1R inhibitors for the metastatic, MYC amplified medulloblastoma tumor cell cultures." (PMID 27255663, 2016). "We then extended the observation that c-MYC amplified medulloblastoma was biochemically responsive to IGF-1 stimulation in D425 cells to CHLA-01-MED cells." (PMID 27255663, 2016). "The development of MYC-driven animal models of medulloblastoma has provided strong support for the role of c-MYC over-expression in the tumorigenesis of Group 3 MB." (PMID 27775567, 2016). "IGF1 led not only to receptor phosphorylation but also accelerated migration/adhesion in MYC amplified medulloblastoma cells in the context of appropriate matrix or meningothelial cells." (PMID 27255663, 2016). "In parallel, studies of key factors responsible for cell autonomous growth in MYC amplified medulloblastoma prioritized IGF1R inhibitors." (PMID 27255663, 2016). "These techniques are also now providing promising new insights into the study of c-MYC-amplified Group 3 medulloblastomas." (PMID 27775567, 2016). "OTX2 has recently been shown to repress differentiation, increase proliferation, and upregulate c-MYC in medulloblastoma cells." (PMID 27775567, 2016). "The tumorigenic role of c-MYC in medulloblastoma is further complicated by RNA-Seq studies showing persistent gene fusions involving the 5′ end of PVT1, a noncoding gene, which frequently coamplifies with c-MYC." (PMID 27775567, 2016). "MYC elevation is more common in Group 3 medulloblastomas and is seen in up to 16.7% of them, but can also occur in some Group 4 or SHH tumors." (PMID 26380221, 2015). "We show in this study that medulloblastoma cells overexpressing MYC are sensitized to apoptosis induced upon Aurora B inhibition." (PMID 25739120, 2015). "GTML transgenic mice represent the only native model of MYC oncoprotein family-driven spontaneous medulloblastoma in which genetically manipulable tumors arise in immunocompetent mice with an intact blood-brain-barrier." (PMID 25785590, 2015). "We have demonstrated the therapeutic potential of Aurora B inhibition in MYC overexpressing medulloblastoma in both a flank and an intracranial xenograft model." (PMID 25739120, 2015). "We here validate MYC amplification as a predictive and routinely applicable clinical biomarker for HDACi sensitivity of medulloblastoma patients." (PMID 25853389, 2015). "Medulloblastoma comprises four molecular subgroups of which Group 3 medulloblastoma is characterized by MYC amplification and MYC overexpression." (PMID 25739120, 2015). "One significant clinical challenge for medulloblastoma in pediatric oncology stands that the overall survival currently remains under 70%, and patients with tumors overexpressing MYC or harboring MYC oncogene amplification have an extremely poor prognosis." (PMID 25849938, 2015). "Establishment of their wider relevance to medulloblastoma at diagnosis, alongside other MYC/MYCN amplified and overexpressing malignancies, is paramount." (PMID 25533335, 2015).
medulloblastoma (continued). "Using both flank and intracranial cerebellar xenografts we demonstrate that tumors formed from MYC-overexpressing medulloblastoma cells show a response to Aurora B inhibition including growth impairment and apoptosis induction." (PMID 25739120, 2015). "Group 3 medulloblastomas are characterized by frequent amplifications of the oncogene MYC, a high incidence of metastasis, and poor prognosis despite aggressive therapy." (PMID 26061748, 2015). "The specific inhibition of Aurora kinase B was achieved in MYC-overexpressing medulloblastoma cells with AZD1152-HQPA." (PMID 25739120, 2015). "Lastly, we show the distribution of AZD1152-HQPA within the mouse brain and the ability to inhibit intracranial tumor growth and prolong survival in mice bearing tumors formed from MYC-overexpressing medulloblastoma cells." (PMID 25739120, 2015). "To further confirm that the JQ1 effects in medulloblastoma cells were a result of suppressing c-MYC we sought to directly evaluate MYC activity." (PMID 24796395, 2014). "Group 4 medulloblastomas are associated with CDK6 and MYCN amplification but minimal MYC over-expression." (PMID 25101241, 2014). "We evaluated the impact of 300nM JQ1 on c-MYC signaling in a well-characterized medulloblastoma cell line (Daoy) using genome wide transcriptional profiling." (PMID 24796395, 2014). "Here we report that MYC driven medulloblastoma can be targeted by inhibition of the bromodomain protein BRD4." (PMID 24796395, 2014). "Both of these cell lines also express high levels of MYC (with D341 harboring genomic copy number gain and D721 exhibiting normal MYC copy number), suggesting that these cell lines belong to the Group 3 medulloblastoma subtype." (PMID 25198066, 2014). "Our work indicates that BRD4 inhibition attenuates stem cell signaling in MYC driven medulloblastoma and demonstrates the feasibility BET domain inhibition as a therapeutic approach in vivo." (PMID 24796395, 2014). "Immunoblotting analysis confirmed that JQ1 decreased expression of the c-MYC protein in medulloblastoma cells." (PMID 24796395, 2014). "All three c-MYC related gene sets were statistically enriched among genes down regulated by JQ1, suggesting that JQ1 supresses MYC driven genomic programs in medulloblastoma." (PMID 24796395, 2014). "To examine the impact of JQ1 in further detail we treated c-MYC translocated D283 medulloblastoma cells with JQ1 and performed immunofluorescence for SOX2." (PMID 24796395, 2014). "In summary we establish the concept that MYC driven medulloblastoma can be targeted with BET domain inhibition and demonstrate the feasibility of this approach in vivo." (PMID 24796395, 2014). "We show that bromodomain inhibition with JQ1 restricts c-MYC driven transcriptional programs in medulloblastoma, suppresses medulloblastoma cell growth and induces a cell cycle arrest." (PMID 24796395, 2014). "Here we show that BRD4 inhibition is a highly effective strategy to inhibit MYC driven medulloblastoma." (PMID 24796395, 2014). "Together these data suggest that BRD4 inhibition can be a highly effective strategy to target tumor stem cells in medulloblastoma and other MYC driven tumors." (PMID 24796395, 2014). "OTX2 transcriptionally regulates cell cycle genes and the MYC oncogene, thereby contributing to medulloblastoma maintenance, and additionally can alter the dynamics of hindbrain progenitor cell migration and proliferation." (PMID 25198066, 2014). "Here we show that the BET domain protein BRD4 is a mediator of medulloblastoma growth in the context of MYC pathway activation." (PMID 24796395, 2014).
medulloblastoma (continued). "We next examined the effect of BET inhibitors on MYC functionality in several genetic backgrounds relevant for human primary medulloblastoma." (PMID 24231268, 2013). "Supporting these previous findings, medulloblastoma cells exhibited a similar reduction of MYC expression following BET inhibition here, and the strongest apoptotic induction occurred in MYC-amplified cell lines." (PMID 24231268, 2013). "Taken together, BRD4 knockdown reduced both MYC expression and viability in the group 3-derived medulloblastoma cell line, HD-MB3, and therefore, phenocopies the effects of JQ1 treatment." (PMID 24231268, 2013). "Taken together, BET inhibition via JQ1 downregulates MYC as well as MYC targets in medulloblastoma cells." (PMID 24231268, 2013). "The HD-MB3 cell line is well-described and one of the few medulloblastoma cell lines originating from a MYC-amplified group 3 tumor." (PMID 24231268, 2013). "High-level gene amplifications are overall rarely observed in medulloblastoma, but when they do occur, they most frequently affect the MYC or MYCN oncogenes and only in a very few cases the related MYCL gene." (PMID 22358457, 2012). "Both MYC and MYCN amplifications further associate with an aggressive LCA medulloblastoma pathology." (PMID 22348395, 2012). "In the absence of miR-33b expression data, these results implicate the association between down-regulation of SREBF1 (the host gene of miR-33b) and MYC overexpression and poor prognosis in medulloblastoma." (PMID 22887866, 2012). "MYC gene amplification is found only in 5–8% of medulloblastoma, suggesting that other mechanisms exist to account for the increased c-Myc expression." (PMID 22887866, 2012). "Our data suggest an important functional interaction between OTX2 and MYC in regulating gene expression in medulloblastoma." (PMID 22016811, 2011). "Together these results suggest that OTX2 and MYC cooperate in regulating gene expression in medulloblastoma." (PMID 22016811, 2011). "The specific bi-modal distribution of OTX2 binding around the TSSs, as we investigated in medulloblastoma, strongly differs from the binding patterns of MYC and other transcription factors like GATA1 and TCF4." (PMID 22016811, 2011). "In this study, we have analyzed the binding of OTX2 to promoter regions in the complete genome and compared the OTX2 data with ChIP-on-chip data for MYC in medulloblastoma." (PMID 22016811, 2011). "Both OTX2 and MYC are important oncogenes in medulloblastoma, the most common malignant brain tumor in childhood." (PMID 22016811, 2011). "A series of novel and established medulloblastoma defects were detected (MYC amplification (n = 4), 17q21.31 high-level gain (n = 1); 9p21.1–p21.3 (n = 1) and 6q23.1 (n = 1) homozygous deletion)." (PMID 19584924, 2009). "Thus, controlling the ribosomal biogenesis at multiple points offers a possible strategy to treat MYC-driven medulloblastoma." (PMID 39779613, 2025). "This review updates recent findings on the crosstalk between MYC and mTOR and targeted therapies that inhibit both MYC and mTOR along with other treatment modalities that hold potential to treat the Group 3 MYC-amplified medulloblastoma at the translational level." (PMID 39779613, 2025). "Cooperation between these two pathways may dysregulate translation globally and promote the pathology of MYC-dependent cancers, including medulloblastoma." (PMID 39779613, 2025). "Furthermore, co-treatment with TEM enhanced MP1 activity in MYC-amplified medulloblastoma cell lines, suggesting a synergistic interaction." (PMID 41149606, 2025). "Some targeted approaches may be explored in the context of MYC-amplified medulloblastoma and mTOR inhibitors." (PMID 39779613, 2025).
medulloblastoma (continued). "These include combination therapy with PI3K pathway inhibitors (BKM-120) and histone deacetylase inhibitors (LBH-589) for MYC-driven group 3 medulloblastoma, targeting LSD1 in MB with GFI1/GFI1B over-activation, CDK inhibitors, and cell cycle checkpoint inhibitors." (PMID 40229260, 2025). "CDK inhibitors could be part of a treatment strategy for MYC-amplified medulloblastoma, although their precise role in controlling this specific cancer subtype is still an active area of research." (PMID 39779613, 2025). "Targeting cancer-selective metabolic vulnerabilities in MYC-amplified medulloblastoma – Sheila Singh from McMaster University, Canada, presented her research on MYC-driven medulloblastoma (MB), an aggressive pediatric brain tumor characterized by therapy resistance and disease recurrence." (PMID 41221269, 2025). "Further, targeting this enhanced protein synthesis pathway with combined inhibition of MYC transcription and mTOR translation by small-molecule inhibitors, demonstrates preclinical synergistic anti-tumor potential against MYC-driven medulloblastoma in vitro and in vivo." (PMID 39779613, 2025). "Targeting such MYC-driven metabolic program using metabolic inhibitors could be one of the promising startegies for MYC-driven medulloblastoma." (PMID 39779613, 2025). "Targeting glycolysis with inhibitors of HK2, LDHA, or PKM2 has shown promise in preclinical models, indicating that disrupting glycolytic flux could be a therapeutic strategy in MYC-driven medulloblastoma." (PMID 40868156, 2025). "C-MYC overexpression has been shown to contribute significantly to the aggressiveness of medulloblastoma, although the effects of exogenous c-MYC expression via the Sleeping Beauty transposon system may differ from endogenous c-MYC in patient tumors." (PMID 40917877, 2025). "While the exact mechanism of the combination therapy is still a subject of ongoing research, there are several ways in which these inhibitors may work together to target MYC-amplified medulloblastoma." (PMID 39779613, 2025). "Based on existing evidence, targeting of MYC and mTOR pathways together produces functional synergy that could be the basis for effective therapies against medulloblastoma." (PMID 39779613, 2025). "Consequently, Group 3 tumors have the worst prognosis among the medulloblastoma subtypes, with five-year survival rates ranging from 50% to as low as 20–30% in cases of metastasis or MYC amplification." (PMID 40868156, 2025). "Additionally, highly aggressive MYC-subgroup medulloblastomas, characterized by c-MYC overexpression, have been modeled in mice, providing a robust platform to study their unique pathobiology and develop targeted therapies." (PMID 40647519, 2025). "It has been suggested that bromodomain and extraterminal domain (BET) bromodomain inhibitors may be promising for treating MYC-driven medulloblastomas." (PMID 41002991, 2025). "In addition, a distinct hotspot area for macrophage aggregation was observed in a single case of MYC-amplified medulloblastoma." (PMID 40303994, 2025). "Amplification of the MYC transcription factor family member MYCN drives a range of solid tumours including medulloblastoma, rhabdomyosarcoma, osteosarcoma, Wilms tumour, small cell lung cancer and retinoblastoma, with MYCN overexpression associated with poorer prognoses." (PMID 38943005, 2024). "Another study revealed that OTX2 works synergistically with MYC in oncogenesis in medulloblastoma." (PMID 38925618, 2024). "As MYC is one of the most “undruggable” targets in cancer biology, alternative approaches targeting downstream pathways might prove useful on the MYC-dependent malignancies such as medulloblastoma." (PMID 39436961, 2024).